SSR2 (signal sequence receptor subunit 2)
Description:
TRAP proteins are part of a complex whose function is to bind calcium to the ER membrane and thereby regulate the retention of ER resident proteins.
Synonyms: TRAP-beta; TRAPB; HSD25; TLAP
Tractability: Antibody: UniProt predicts a signal peptide or a membrane-spanning region. PROTAC: ubiquitination databases record sites on it.
Gene: Protein-coding gene on chromosome 1 (156,009,041 to 156,020,968, reverse strand). Ensembl gene ENSG00000163479.
Subcellular location: Endoplasmic reticulum membrane
Pathways (Reactome):
Metabolism of proteins: SRP-dependent cotranslational protein targeting to membrane
Gene Ontology:
Molecular function: protein binding
Biological process: cotranslational protein targeting to membrane; post-translational protein targeting to membrane, translocation
Cellular component: endoplasmic reticulum; endoplasmic reticulum membrane; membrane; translocon complex
Genetic constraint (gnomAD): Loss-of-function variants: 9 observed, 15.91 expected, observed/expected ratio (o/e) 0.57, 90% interval 0.34 to 0.99. The upper end of that interval is the gene's LOEUF score, 0.99, which puts it in group 4 of 6, group 1 being the genes least tolerant of losing a copy. Missense variants: 161 observed, 217.09 expected, observed/expected ratio (o/e) 0.74, 90% interval 0.65 to 0.85. Synonymous variants: 78 observed, 89.44 expected, observed/expected ratio (o/e) 0.87, 90% interval 0.73 to 1.05.
Homologues: Orthologues: macaque SSR2 (99% identical), pig SSR2 (98% identical), guinea pig SSR2 (97% identical), mouse Ssr2 (97% identical), dog SSR2 (96% identical), rat Ssr2 (91% identical), chimpanzee SSR2 (90% identical), tropical clawed frog ssr2 (87% identical), zebrafish ssr2 (86% identical), rabbit SSR2 (79% identical), Drosophila melanogaster SsRbeta (49% identical), Caenorhabditis elegans trap-2 (39% identical), and 1 more.
Diseases named in the same sentence as SSR2 in open-access papers:
SSR2 is named in the same sentence as 19 diseases in open-access papers, as found by Europe PMC text mining. Sharing a sentence is not in itself a finding about the gene and the disease. The quoted sentences say what the papers report.
hepatocellular carcinoma (6 papers, 2017 to 2026). A malignant tumor that arises from hepatocytes. "Through constructing tissue microarray, we have identified that SSR2 was highly expressed in HCC tumor tissues compared with adjacent normal tissues of hepatocellular carcinoma patients by immunohistochemistry assays." (PMID 32913453, 2020). "SSR2 is a subunit of SSR protein, but the role of SSR2 in hepatocellular carcinoma is largely unknown and warrants further study." (PMID 32913453, 2020).
meningioma (3 papers, 2022). A generally slow growing tumor attached to the dura mater. "The relationship among 68Ga-DOTATATE meningioma uptake, considered a surrogate biomarker of SSR2 expression, and tumor growth rate (TGR) was evaluated by Sommerauer and coworkers in 23 subjects with an overall number of 64 lesions." (PMID 35885570, 2022). "In particular, SSR2 has been reported in meningioma tissues, thus is being considered for clinical applications based on its molecular characteristics." (PMID 35847854, 2022). "Among SSRs, the subtype 2 (SSR2) has been found overexpressed in meningiomas and has catalyzed attention as a potential target for diagnosis and therapy." (PMID 35885570, 2022). "Another study reported five cases of meningioma en plaque without previous bone decalcification, showing that all cases histopathologically were strongly positive for SSR2 and associated with intralesional features similar to oncogenic osteomalacia." (PMID 35847854, 2022).
craniosynostosis (1 paper, 2018). Craniosynostosis is defined as the premature fusion of one or more cranial sutures leading to secondary distortion of skull shape resulting in skull deformities with a variable presentation. "Out of seven genes with a high (< 10%) or moderate (< 25%) HI score (NES, CCT3, MEF2D, LAMTOR2, ETV3, SSR2, NTRK1), none of them have been linked to craniosynostosis." (PMID 29845577, 2018).
esophageal cancer (1 paper, 2024). A primary or metastatic malignant neoplasm involving the esophagus. "Among negatively correlated genes, a higher expression of CLDNI5 and IL2RG, and was seen in esophageal cancer than normal tissue (p < .05), but the converse was true for DGKD, CLDNI8, TMEM220-AS1, TMEM220, C3orf86, and SSR2 (p < .0.05)." (PMID 38241178, 2024).
melanoma (1 paper, 2022). A malignant, usually aggressive tumor composed of atypical, neoplastic melanocytes. "Through the translocation of proteins necessary for URP, SSR2 may be particularly implicated in melanoma cells' resistance to ER stress." (PMID 36003068, 2022).
tumor (9 papers, 2020 to 2026). "Our results have indicated that SSR2 overexpression in tumor tissues was associated with survival of HCC patients." (PMID 32913453, 2020). "Our results revealed that SSR2 was strongly associated with encapsulation invasion, and tumor grade." (PMID 32913453, 2020). "However, additional experiments are required to delineate the detailed molecular mechanisms underlying how SSR2 was upregulated in HCC tumor tissues and how SSR2 promotes proliferation, migration and invasion of HCC cells." (PMID 32913453, 2020). "RT‐PCR result showed that the expressions of SSR2 was also significantly downregulated in shSSR2‐2 group tumour samples compared with shCtrl group." (PMID 35481617, 2022). "Meanwhile, matched tumor sample showed high levels of SSR2, Iba1 (26.5%), and TMEM119 (39.5%), and moderate levels of CD206 (8.81%) and CD163 (11.9%)." (PMID 35534852, 2022). "In keeping with the results of the GEPIA analysis, we found that only SSR2 was differentially expressed in tumor and normal samples by qRT-PCR." (PMID 36003068, 2022). "Overexpression of MDK, CENPM, and SSR2 promotes tumor metastasis, angiogenesis, and tumorigenesis, leading to poor prognosis in patients with HCC." (PMID 34900444, 2021). "From our clinical specimens, the expression of SSR2 was much higher in tumor tissues compared with that in adjacent non-tumor tissues." (PMID 33485374, 2021). "To make clear the role of SSR2 in tumor progression, we tentatively examined the expression of SSR in various cancers." (PMID 32913453, 2020). "SSR2 depletion also repressed the tumour growth of HCC cells in vivo." (PMID 35481617, 2022). "From the H&E results, we found that the number of metastatic tumor nodules in shSNHG14 group was the least and SSR2 overexpression could partially restore the tumor number in lungs." (PMID 33485374, 2021). "Consistent with our in vitro observations, knocking down of SNHG14 resulted in significant decrease of tumor volume and tumor weight; while the overexpression of SSR2 could partially restore the inhibitor effects of shSNHG14." (PMID 33485374, 2021). "Collectively, we could conclude that SNHG14 exerted its tumor-promoting effects through miR876-5p/SSR2 axis in a ceRNA model." (PMID 33485374, 2021). "Additionally, 105 pairs of HCC tissues indicated that SSR2 was upregulated in HCC tissues compared with adjacent non-tumor tissues." (PMID 33485374, 2021). "Importantly, in our previously collected tumor tissues and corresponding non-tumor tissues, we discovered that SSR2 mRNA expression was markedly elevated in tumor tissues." (PMID 32913453, 2020). "To determine the relationship of SSR2 expression and clinicopathological characteristics, we analyzed the relationship of SSR2 expression and the clinical parameters, high expression of SSR2 was positively correlated with encapsulation invasion (p=0.01) and tumor grade (p=0.03)." (PMID 32913453, 2020). "Data mining in TCGA and GEPIA databases results supported our hypothesis that SSR2 was overexpressed in HCC tumor tissues." (PMID 32913453, 2020). "In this study, we discovered that SSR2 was upregulated in HCC tumor tissues." (PMID 32913453, 2020). "Consistently, SSR2 expression was elevated in tumor tissues compared with adjacent normal tissues." (PMID 32913453, 2020). "Notably, the authors also performed histochemical analysis of SSR2 expression on tumor specimen and found a correlation between SSR2 density and tracer uptake in tumors (i.e., SUVmax), being the SUVmax threshold of 2.3 suitable for discriminating between tumor and tumor-free tissue." (PMID 35885570, 2022). "We discovered SSR2 expression was elevated compared with the corresponding adjacent normal tissues, From our tissue microarray, we found that high SSR2 expression accounts for about 65.6%, while most of adjacent non-tumor tissues, SSR2 expression was quite low." (PMID 32913453, 2020).
tumor (continued). "Next, a xenograft tumor model was performed to demonstrate the role of SSR2 in the absence of SNHG14 in vivo." (PMID 33485374, 2021).
cancer (3 papers, 2019 to 2020). A tumor composed of atypical neoplastic, often pleomorphic cells that invade other tissues. "SSR2 has been shown to be a reliable cancer biomarker for LIHC." (PMID 31824949, 2019). "Notably, FUT11, BGLAP, SSR2, TGFBR1, BSG, and FUCA1 have been reported to be associated with related cancer, but no studies showed the functions of other eight DESPGs in corresponding cancers." (PMID 31824949, 2019).
SSR2 also shares sentences with these, for which no sentence is quoted: liver fibrosis (2 papers); breast carcinoma (1); endometrial carcinoma (1); fibrosis (1); hematological malignancies (1); Kidney (1); liver cancer (1); pancreatic cancer (1); pilocytic astrocytoma (1); Thyroid carcinoma (1); viral infection (1); ZIKV infection (1).